IL6 (interleukin 6)
Diseases named in the same sentence as IL6 in open-access papers (continued):
Sharing a sentence is not in itself a finding about the gene and the disease.
asthma (continued). "The elevation of IL-6 and IFN-γ in children suggests that non-T2 asthma in this population is a more inflammatory phenotype, potentially predisposing to frequent exacerbations, accelerated airway remodeling, and corticosteroid resistance." (PMID 41601686, 2026). "In the pediatric cohort, children with non-T2 asthma displayed a prominent non-T2 inflammatory signature, with significantly higher serum IL-2, IFN-γ, IL-6, and IL-17A compared with T2-high children (p < 0.05 for all indicated comparisons)." (PMID 41601686, 2026). "Our analyses of nasal and bronchial biopsies from patients with asthma established a clear correlation between elevated IL6 gene expression, IL6TS signatures and IL6 gene methylation." (PMID 41099307, 2026). "Meng and Zhu found that administration of recombinant human IL-37 protein, either via intranasal inhalation or intravenous injection, effectively reduced levels of IL-4, IL-5, IL-6, and IL-13 in a chronic HDM-induced asthma model." (PMID 41293155, 2025). "In the obese asthma model, FIP-fve markedly attenuated Der p-induced AHR and decreased serum levels of pro-inflammatory and allergic markers, including IL-6, IL-33, osteopontin, and VCAM-1." (PMID 40998975, 2025). "As described in the features section, each disease class was mapped to literature-supported protein and gene expression profiles (MMP-9 and TGF-β for bronchiectasis, CRP and IL-6 for pneumonia, and IL-5 and YKL-40 for asthma)." (PMID 40806268, 2025). "A causal relationship exists between genetically determined protein levels of IL1R1, IL7R, ECM1, CD200R1, ADAM19, IL-6 sRa, and Layilin (LAYN) and asthma." (PMID 39806440, 2025). "The inflammatory process also increases the synthesis of proinflammatory cytokines such as interleukin (IL)-6, tumor necrosis factor-α (TNF-α), IL-1β, and transforming growth factor-β (TGF-β), all contributing to asthma pathogenesis and severity." (PMID 40083433, 2025). "In severe asthma, macrophages adopt the M1 phenotype and produce a large amount of pro-inflammatory mediators (including TNF-α, IL-1β, IL-6, NO, etc.)that promote airway mucus secretion, exacerbate lung injury, and accelerate airway remodeling." (PMID 40661956, 2025). "The direct effect of asthma leading to osteoporosis is related to disease inflammation (e.g., neutrophil-mediated inflammation, TNF-α and IL-6)." (PMID 39857779, 2025). "Regulatory T cell modulates the balance of Th1 and Th2 cells and Treg cell-related cytokines such as IL-6 and TNF-6 play an important role in asthma." (PMID 40323927, 2025). "Elevated levels of proinflammatory mediators such as substance P, interleukin-6 (IL-6), and C-reactive protein (CRP) have been observed in both conditions, biologically supporting the coexistence of asthma and fibromyalgia." (PMID 41017472, 2025). "In our study, the relative expression of IL‐6, a proinflammatory cytokine that increases in the BALF of horses with moderate asthma, significantly decreased over time in treated horses." (PMID 39945569, 2025). "Proinflammatory cytokines (TNF-α, IL-6) and profibrogenic mediators (TGF-β1, IL-13) also play significant and distinct roles in asthma pathogenesis." (PMID 40573126, 2025). "Pro-inflammatory cytokines such as IL-6 and TNF-α, which are elevated in asthma, can stimulate bone resorption, reducing bone mineral density (BMD)." (PMID 39857779, 2025). "The targets of the FEO‐03 network, IL13, and functional partners IL13RA1, IL13RA2, IL4R, IL6, and TNF were presented in a red box from the asthma diagram of KEGG Pathways." (PMID 40777200, 2025).
asthma (continued). "Human studies are more limited, but preliminary evidence suggests that fasting decreases interleukin-6 (IL-6) and MCP-1,21 circulating CD4+ T cells numbers and activation markers, and Th2 activation in inflammatory conditions such as asthma." (PMID 40662191, 2025). "We examined the correlations of serum IL-36 levels with serum IL-6, IL-8, IL-10, IL-13, IL-17, IFN-γ, and TNF levels, except for IL-4 and IL-5 levels, which were only rarely observed in our asthma patients." (PMID 40115968, 2025). "In patients with severe asthma, pro-inflammatory cytokines in the airway lumen and bronchial mucosa, including TNF-α, IL-1β, IL-6, and IL-8, are mainly produced by macrophages, while LPS can stimulate THP-1 cells to secrete pro-inflammatory cytokines." (PMID 40661956, 2025). "Colocalization analysis indicated that ECM1 (coloc.abf-PPH4 = 0.953), IL-6 sRa (coloc.abf-PPH4 = 0.966), and layilin (coloc.abf-PPH4 = 0.975) shared the same genetic variation as in asthma." (PMID 39806440, 2025). "Taurine, a semi-essential amino acid and potent antioxidant, inhibits pro-inflammatory cytokines (IL-1, IL-6, and TGF-β) and is elevated in plasma and bronchoalveolar lavage fluid of asthma patients." (PMID 40722500, 2025). "Our findings illustrated that in the serum of children with BA, miR‐27a‐3p targets ATF3 and inhibits ATF3 levels, promotes airway inflammation, and upregulates the levels of IL‐17, IL‐6, TNF‐a, and EOS, thereby promoting the occurrence of asthma." (PMID 37385291, 2025). "Through colocalization analysis of the seven initially identified proteins, three proteins were identified as potential drug targets for asthma, including ECM1, IL-6 sRa, and layilin." (PMID 39806440, 2025). "Our study demonstrated a causal relationship between genetic determinants, including IL1R1, IL7R, ECM1, CD200R1, ADAM19, IL-6 sRa, and Layilin (LAYN) protein levels, and asthma." (PMID 39806440, 2025). "The reduction in inflammatory factors such as TNF-α and IL-6, as well as the decreased expression of the important inflammatory pathway NF-κB/COX-2/PGE2, contributed to the effective control of asthma-related changes." (PMID 40323927, 2025). "Direct targeting of the 3’UTR region of STAT3 by exosome miR-301a-3p reduced the release of inflammatory cytokines TNF-α, IL-1β, and IL-6, which can inhibit OVA-induced asthma." (PMID 39444792, 2024). "Fluconazole-treated asthma mice displayed higher levels of cytokines in serum and lung tissue (TNF-α and IL-6), increased pathological scores, and a higher number of mononuclear cells in BALF, with undetectable fungal levels compared to untreated mice." (PMID 39484217, 2024). "Furthermore, given that non-eosinophilic asthma, which is characterized by neutrophilia, is driven by cytokines seen in PTSD including IL-1α, IL-6 and IL-17, we hypothesized that individuals with asthma and PTSD would have distinct inflammatory markers compared to those without PTSD." (PMID 38349898, 2024). "Several studies have noted a decrease in various cytokines such as IFN-γ and IL-10, along with higher levels of both IL-6 and IL-8, suggesting an overactivation of pro-inflammatory mechanisms in patients with hemoglobinopathies, which could trigger inflammatory conditions such as asthma." (PMID 38892971, 2024). "PD1 downregulated IFN-γ and TNF-α in patients with severe asthma, and PD1 alleviated infiltration and extracellular traps of neutrophils with decreased IL-6 and TNF-α in LPS-induced acute lung injury." (PMID 39720728, 2024). "Inflammation observed in Asthma-COPD Overlap Syndrome (ACOS) is primarily driven by eosinophils and neutrophils, as evidenced by studies demonstrating significantly elevated levels of IL-6 in ACOS patients compared to healthy individuals and those with asthma." (PMID 38919942, 2024).
asthma (continued). "Activated eosinophils secrete a variety of cytokines during the development of asthma, including Th2 cytokines (IL-4 and IL-5), acute proinflammatory cytokines (e.g., TNF-α, IL-6, and IL-8) and chemokines." (PMID 38245791, 2024). "Influenza viruses provoke elevated levels of pro-inflammatory cytokines, such as IL-6, TNF-α, and interferons, worsening airway inflammation and airflow limitation in COPD and asthma." (PMID 39458339, 2024). "Through literature search, we found that the research on IL6, EGFR, and HIF1A to asthma was relatively richer compared with these of other targets." (PMID 38590639, 2024). "Key cytokines such as interleukin (IL)-6, IL-8, and tumour necrosis factor-alpha (TNF-α) play critical roles in driving airway inflammation and bronchial hyperreactivity." (PMID 39458339, 2024). "Small molecule inhibitors, such as JAK-inhibitors, and monoclonal antibodies targeting mast cells, IL-1, IL-6, IL-33, TNFα, and OX40L are under investigation for their potential to modulate inflammation involved in refractory asthma." (PMID 39194521, 2024). "Knockdown of RYR2 also inhibited the increase in proinflammatory cytokines, including IL-1β, IL-6, and TNF-α, in rats with asthma and spinal cord injury." (PMID 37422673, 2023). "Both IL-6 and TNF-α are clinically proven inflammatory cytokines found in various types of asthma induced by allergens." (PMID 37998734, 2023). "In the present study, there was an increase in the inflammatory markers involved, such as IL-1β, IL-4, IL-5, IL-6, IL-10, IL-13, IL-17, IFN-γ, and TNF-α, in the experimental model of asthma-COPD overlap." (PMID 37511021, 2023). "The CC genotypes of IL4rs2243250, IL6 rs1800795, IL13 rs1800925, as well as theGG genotype of TNFA rs1800629 were shown in our study tobe protective against the development of mild asthma." (PMID 37465198, 2023). "This treatment significantly decreased inflammation markers like monocyte chemotactic protein 1, IL-4 and IL-6 levels in both COPD and asthma patients." (PMID 38067515, 2023). "It was found that in co-culture, CD4+ T cells had an increased release of IL-17 and IL-22 and induced an increased release and mRNA expression of IL-6, IL-1β, TGF-β and IL-23 in asthma-derived HBFs compared to controls." (PMID 36911735, 2023). "The cytokine production of IL-6, CCL-2, and IL-12p40 in the lungs and BAL significantly increased after viral challenge in both the naïve-infection and asthma-infection groups." (PMID 37424011, 2023). "In our asthma mouse model sensitized with OVA, the lung tissues were significantly damaged and the contents of inflammatory cytokines (IL-17A and IL-6) were considerably increased, while the content of IL-10 was significantly decreased." (PMID 36743692, 2023). "The complex IL-6/IL6R triggers a cascade that activates STAT3 and CEBP transcription factors, both involved in airway inflammation and asthma." (PMID 36979655, 2023). "MCP-1, IL-6, and TNF-α are key chemokines or cytokines involved in lung diseases, including asthma and COPD." (PMID 37045933, 2023). "Various experiments on the effects of NPs on lung disorders, such as asthma, COPD, and other lung diseases, indicated that nanoparticles suppressed proinflammatory mediators, such as IL-6, IL-8, IL-1β, and TNF-α." (PMID 37538179, 2023). "Interestingly, high levels of IL-6 have been shown to induce the systemic release of NETs in other inflammatory diseases of respiratory disease such as severe asthma and chronic obstructive pulmonary disease, and statins may reduce IL-6 release under inflammatory conditions." (PMID 36853269, 2023). "SA ILC2s demonstrated a 100‐fold increased release of IL‐6 following stimulation with IL‐2, IL‐33, IL‐25 and TSLP compared to mild asthma and the controls." (PMID 37114915, 2023). "The obese asthma phenotype is also related to the increased production of pro-inflammatory cytokines—TNF-α and IL-1β in the lung, and IL-6 in serum." (PMID 37367676, 2023).
asthma (continued). "The expression of IL-6 and TNF-α in asthmatic patients is closely related to the severity of asthma symptoms." (PMID 37492220, 2023). "We found that exercise intervention can effectively reduce IL-6 and TNF-α levels in children with asthma." (PMID 37492220, 2023). "Asthma inflammation is well immunomodulated by thymoquinone extract, which inhibits IL-2, IL-6, and PGE2 in T cells and IL-6 AND PGE2 in monocytes." (PMID 36684115, 2023). "IL-6, IL-1 and TNF-α are highly expressed in the BALF of asthma patients; these cytokines induce airway inflammatory cell infiltration and airway injury and aggravate bronchial hyperresponsiveness." (PMID 36691058, 2023). "Clinical observations have especially shown that the proinflammatory cytokines mainly produced by macrophages (e.g., TNF-α, IL-1β, IL-6, and MCP-1) are increased in the BALF of patients with asthma." (PMID 37107297, 2023). "The top six upregulated DEG genes (IL6, CXCL8, TNF, DUSP2, ADM, and CXCL1) in SR asthma patients compared with SS asthma patients were identified." (PMID 37208441, 2023). "While IL‐6 is usually considered to be triggered in response to type 1 or type 17 immune responses our results demonstrate a more complex picture where ILC2s may contribute to its release and its effects in severe asthma, though the mechanisms of this remain to be defined." (PMID 37114915, 2023). "They claimed that the link between asthma-T2DM and asthma-CHD is likely due to the shared immunogenic and environmental factors, such as the production of inflammatory cytokines IL-6 and IL-17, which have been found in both of these diseases." (PMID 37056543, 2023). "CAD significantly decreased the content of TNF-α, IL-13, IL-4, IL-1β and IL-5 in the bronchoalveolar lavage fluid (BALF), IL-17, IL-6, and OVA-specific IgE in serum and increased serum IFN-γ in asthma mice." (PMID 36213326, 2022). "Beyond Th2 cytokines, SAT also reduced the levels of other potent proinflammatory cytokines (IL-1β, IL-6, and TNF-α) which also plays a key role in asthma pathophysiology and progression, accounting to disease severity." (PMID 36312895, 2022). "Neutrophilic asthma and airway remodeling are not fully understood, but several studies have shown that inflammatory mediators, such as LTB4, IL-6, IL-8, and TNF-α, which are related to neutrophilic inflammation, were elevated in an asthmatic airway." (PMID 35626330, 2022). "Among these, IL6 and IL4 were screened out as highly potential biomarkers in childhood asthma since the gene also acquired a high systemic score in Cytohubba’s MCC algorithm." (PMID 36140412, 2022). "Asthma can regulate the HIF-1 signaling pathway, promoting the expression of IL6, Stat3, and HIF-1α protein and mRNAs, so as to promote sperm apoptosis and ultimately causing male infertility." (PMID 35620222, 2022). "In this study, we constructed the PPI network; IL6, CASP3, EGFR, MAPK8, ESR1, CCND1, and PPARG were found to be the core genes of YPF in treating asthma." (PMID 36105239, 2022). "To evaluate the effects of simultaneous administration of TNF and IL-6 inhibitors, we measured the number of Th17-cells in the lungs of mice with HDM-induced asthma." (PMID 35408882, 2022). "At four weeks, later occurrence of AD, CMA, and asthma was positively correlated with calprotectin (r = 0.61), IL-1β (r = 0.58), EDN (r = 0.57), and TGF-β (r = 0.57), and negatively correlated with IL-6 (r = −0.71) and IL-10 (r = −0.61)." (PMID 35628877, 2022). "To evaluate the potency of combined cytokine inhibition, we simultaneously administrated IL-6 and TNF inhibitors to BALB/c mice with HDM-induced asthma." (PMID 35408882, 2022). "However, this might be a therapy for systemic IL-6-driven asthma in the future." (PMID 35722499, 2022). "Among 10 hub genes, we strongly suggest IL6 and IL4 as prospective childhood asthma biomarkers since both of these biomarkers achieved a high systemic score in Cytohubba’s MCC algorithm." (PMID 36140412, 2022).
asthma (continued). "IL-6, TNF, and AKT, which occupied an important position in asthma and IPF, are essential targets regulated by BSYQ decoction." (PMID 35672815, 2022). "The lungs of patients with asthma are in a state of inflammation, showing high levels of TNF-α and IL-6 in lung tissue and BALF, mainly released by activated macrophages." (PMID 35682783, 2022). "In an experimental asthma rat model, CBD diminished airway inflammation and IL-4, IL-5, IL-13, IL-6, IL-7 and TNF-α serum levels, which contribute to fibrosis and asthma pathophysiologies." (PMID 36556483, 2022). "Macrophage-released cytokines and chemokines (TNF-α, IL-1β, IL-6, and MCP-1) affect airway inflammation in asthma pathogenesis." (PMID 36499236, 2022). "When activated by FcεRI, mast cells release IL-1β, IL-6, IL-13, and TNF-α, which are involved in the pathology of asthma." (PMID 35266441, 2022). "In our study, HDM stimulation upregulated FGF2 expression levels in both AECs and the asthma mouse model, and FGF2 pre-treatment recruited subepithelial neutrophils in vivo and promoted IL-1β-induced IL-6 and IL-8 secretion in vitro." (PMID 35093168, 2022). "Allergic events (asthma or cow’s milk allergy) and atopic dermatitis were also positively correlated with EDN, IL-1β, IL-10, and IL-6 at four and six weeks." (PMID 35628877, 2022). "Proinflammatory cytokines such as IL-1β, IL-6 and TNF-α are found in increased amounts in the sputum and BALF of patients with asthma." (PMID 35804727, 2022). "This study shows that asthma can regulate the HIF-1 signaling pathway, promoting the expression of IL6, Stat3, and HIF-1α protein and mRNAs, so as to promote sperm apoptosis and ultimately causing male infertility." (PMID 35620222, 2022). "IL6, IL-1β, TNF, VEGFA, AKT1, etc., played an essential role in the PPI network, indicating the crucial roles in treating asthma and IPF." (PMID 35672815, 2022). "M1 macrophages and M1 cytokines (IL-6, IL-1β, and TNF-α) are involved in neutrophilic airway inflammation in asthma." (PMID 35572500, 2022). "IL-1β, IL-6, and MMP-9, which are regulated by the NF-κB pathway, are major mediators of airway inflammation and remodeling in asthma." (PMID 36313381, 2022). "However, these two articles did not study the relationship between other allergic diseases with IL6 gene polymorphisms and did not concern the two other polymorphisms of the IL-6 (rs1800796 and rs1800797), although the associations between these SNPs and asthma have been reported." (PMID 35368692, 2022). "Our findings indicated that pro-inflammatory and pro-fibrotic mediators are increased at the baseline in BSMCs from both asthma and COPD, and that TLR3 agonist polyI:C, significantly upregulated IL-6, IFN-β1, CCL2, FN1 and COL1A1 expressions in BSMCs." (PMID 34512638, 2021). "In chronic obstructive pulmonary disease patients, the PVT1 expression positively correlated with the GOLD stage and levels of TNF-α, IL-6, IL-8, and IL-17; PVT1 exacerbates the inflammation and cell-barrier injury during asthma by regulating miR-149." (PMID 33506021, 2021). "Prioritization of druggable genes reveals known (IL4R, TSLP, IL6, TNFSF4) and potentially new therapeutic targets for asthma." (PMID 34103634, 2021). "As shown by the analysis results of the PPI network topology, 13 key targets were screened, and most were inflammatory cytokines, it is worth to note that IL-6, TNF-α, and IL-10 play an important role in the development of asthma." (PMID 34880921, 2021). "However, the associations between IL-6, ferroptosis and asthma have not been reported." (PMID 34402724, 2021). "In mice HDM-induced severe asthma a combination of TNF and IL-6 inhibitors prevented IL-6-dependent eosinophilia as IL-6 neutralization helped to suppress the pathological side effects associated with systemic TNF neutralization." (PMID 34084159, 2021).